SOCS1 (suppressor of cytokine signaling 1)
Diseases named in the same sentence as SOCS1 in open-access papers (continued):
Sharing a sentence is not in itself a finding about the gene and the disease.
tumor (continued). "Mapping of the SOCS1 mutations over the coding region showed a pattern similar to that observed in other tumor suppressor genes." (PMID 26336985, 2015). "It has been reported that SOCS1 inhibits cell growth, induces senescence and modulates cell cycle arrest resulting in G1 arrest in T cells, fibroblasts or tumor cells, and these effects were associated with upregulation of p21." (PMID 25893382, 2015). "Macrophage-specific deletion of SOCS1 leads to reduced susceptibility to melanoma growth and colon carcinogenesis through increased anti-tumor responses and a switch to M1 polarization of tumor-associated macrophage." (PMID 25120543, 2014). "Thereby, assessment of the SOCS1 mutation status represents a novel tumor-derived, single gene prognostic biomarker in DLBCL." (PMID 23296022, 2013). "Thereby the SOCS1 gene mutation status is a novel tumor-derived, single gene biomarker with prognostic relevance in DLBCL." (PMID 23296022, 2013). "Thereby, SOCS1 mutation status is a novel tumor-derived, single gene biomarker with molecular and prognostic implications in DLBCL." (PMID 23296022, 2013). "Our laboratory has also demonstrated that exogenously administered IFN-α induced profound in vivo anti-tumor activity that was immune-mediated (via CD8+ T cells) in SOCS1 and SOCS3 deficient mice." (PMID 20398276, 2010). "There was a trend for tumours with lower SOCS1 expression levels to be associated with shorter DFS and OS times." (PMID 20433750, 2010). "Methylation of the SOCS-1 gene is associated with lymph node metastasis, advanced tumor stage and reduced expression of SOCS-1 in GC tissues." (PMID 17559667, 2007). "Indeed, miR-155-mediated downregulation of SOCS1 has been associated with increased tumor aggressiveness and resistance to immune checkpoint inhibitors in OSCC." (PMID 40427514, 2025). "Interestingly, in tumor tissues, high expression levels of SOCS1, both at the mRNA and protein levels, have been consistently associated with tumor invasion and thickness." (PMID 37720228, 2023). "More recently, Wand and colleagues tested the therapeutic efficacy of a SOCS-1-silenced DC vaccine loaded with two tumour-associated antigens, survivin and MUC-1 in patients with relapsed acute leukemia (AL) after allogenic hematopoietic stem cell transplantation (allo-HSCT)." (PMID 30717461, 2019). "SOCS1 expression in breast tumor tissues and cell lines might be caused by proinflammatory cytokine, growth hormone, and prolactin in the tumor microenvironment, which result in the loss of sensitivity to subsequent prolactin stimulus." (PMID 28228755, 2017). "The expression of SOCS1 is associated with clinical stages of tumor." (PMID 28228755, 2017). "In addition to STAT3, these included SMARCA2, a tumor suppressor involved in various cancers, SOCS1, a STAT-inhibitor, DNMT3A, with known somatic mutations in the context of clonal hematopoiesis and PPP3CA encoding calcineurin-A, involved in T-cell receptor signaling." (PMID 34874980, 2021). "In this regard, Hodgkin lymphoma exosomes enriched in miR-21-5p and miR-155-5p further contribute to immune evasion by suppressing SOCS1 and amplifying Treg cell expansion, which dampens anti-tumor effector responses." (PMID 40981381, 2025). "One well-characterized oncomiR, miR-155, promotes cancer progression by downregulating tumor suppressors such as SOCS1 (Suppressor of Cytokine Signaling 1) and RAD51 (DNA repair protein)." (PMID 40874062, 2025). "Inhibition of SOCS1 promotes sustained inflammatory signaling and can facilitate tumor immune escape." (PMID 40981381, 2025). "DNMT1 produces hypermethylation of the genes’ promoter regions coding for the cell adhesion molecule 1 (CADM1) and suppressor of cytokine signaling (SOCS1), which are suppressors of malignant tumor development." (PMID 40510497, 2025).
tumor (continued). "Genetic engineering of TILs via CRISPR/Cas9 to delete inhibitory regulators like CISH or SOCS1 has shown promise in preclinical models, leading to enhanced tumor infiltration, polyfunctionality, and complete tumor regression." (PMID 40475782, 2025). "Curcumin was also found to influence epigenetic regulation by inhibiting histone deacetylases (HDACs), leading to increased expression of tumor‐suppressor genes such as SOCS1 and SOCS3." (PMID 40927046, 2025). "We grouped the patients based on tumor cell EBV status and SOCS1 mutational status because of its pathobiological importance." (PMID 40198333, 2025). "In the context of epigenetic alterations, DNA hypermethylation of tumor suppressor genes (e.g., GSTP1, RASSF1A, and SOCS1), have been widely reported in HCC tissues and are associated with more aggressive tumor behavior and lower survival rates." (PMID 40601653, 2025). "This duality of SOCS1 is also manifested in its behavior either as an oncogene or as a tumor suppressor depending on cellular context." (PMID 40512405, 2025). "Patients in the EBV-negative (EBV−) & SOCS1 mutated (m) cluster had more extensive disease based on significantly higher serum TARC (sTARC) levels, higher metabolic tumor volume and increased risk of treatment failure." (PMID 40198333, 2025). "SOCS1 expression in macrophages is associated with a more aggressive tumor phenotype, while SOCS3 correlates with an anti-tumor response." (PMID 41230456, 2025). "Expression of suppressor of cytokine signaling-1 (SOCS1) prevents the activation of the JAK/STAT signaling pathway (a pathway that promotes tumor development)." (PMID 38455038, 2024). "Development of such models, also expressing surrogate tumor antigens, would help test the effectiveness of restoring endogenous SOCS1 expression and testing its impact on antitumor immune responses." (PMID 38415248, 2024). "Recently, it has been reported that this molecule and even the SOCS1-mimetic peptide Tkip can modulate anti-tumor immunity depending on its expression level in anti-tumor lymphocytes and tumor cells via diverse mechanisms." (PMID 39596207, 2024). "Among the potential tumor suppressor mechanisms of SOCS1, only the regulation of the oncogenic function of p21 is genetically proven, and all other mechanisms remain to be tested." (PMID 38415248, 2024). "Targeting the SOCS1 SH2 structural domain with single guide RNA (sgRNA) via CRISPR/Cas9 to inactivate Socs1 in engineered T cell can enhance the reactivity of transferred T cells to cytokines and inhibit tumor growth in mice." (PMID 39342365, 2024). "The cell-intrinsic tumor suppressor functions of SOCS1 and its potential contribution to antitumor immune responses raised the possibility of restoring SOCS1 expression to control tumor growth." (PMID 38415248, 2024). "This analysis identified that SOCS1 expression is predominantly found in clusters 4, 6, 9, and 14, showing high levels in tumor cells and T cells, with moderate a expression in oligodendrocytes and macrophages." (PMID 39654174, 2024). "As SOCS1 expression at steady state is very low and is highly induced by mitogenic cytokines, growth factors and oncogenic growth signaling, SOCS1 is very well poised to play a key role tumor immune surveillance." (PMID 38415248, 2024). "SOCS1 is a tumor suppressor in cancer cells that downregulates cytokines by inhibiting the JAK/STAT pathway." (PMID 38521953, 2024). "These exosomes significantly slowed tumor growth, inhibited macrophage polarization to M2 phenotype, and regulated the suppressor of cytokine signaling 1 (SOCS1) expression by delivering functional miR-155-5p." (PMID 39367471, 2024). "SOCS1 can also modulate antitumor immunity in different ways depending on its expression level in antitumor lymphocytes and in tumor cells." (PMID 38415248, 2024). "In conclusion, this study showed that IL-6 induces CD155 expression in tumor cells and identified SOCS1 as a negative regulator of this process." (PMID 39596207, 2024).
tumor (continued). "The question arises, why SOCS1 can display both tumor suppressing and promoting activity within different and sometimes the same cell type." (PMID 38711523, 2024). "SOCS1 silencing has been identified across multiple tumour types; this is due to frequent epigenetic and micro-RNA mediated suppression of its gene expression." (PMID 39676878, 2024). "Hematoxylin and eosin (H&E) staining confirmed that miR-6794-5p overexpression increased tumor size, which was reduced by SOCS1 overexpression (middle); SOCS1 expression was confirmed in each group (bottom)." (PMID 38521953, 2024). "SOCS1 gene therapy using adenoviral vectors in experimental models has been reported to reduce tumor growth by inhibiting oncogenic signaling and improving CD8+ T cell responses." (PMID 38415248, 2024). "On the one hand, tumor cells with low or null SOCS1 expression, such as the A-549 and NCI-H1437 cell lines, would overexpress CD155 in response to IL-6." (PMID 39596207, 2024). "Pairwise analysis of SOCS1’s expression in tumor and normal samples from the TCGA database revealed varying levels of expression across different cancers." (PMID 39654174, 2024). "Our findings indicate that maintaining sensitivity to oxidative stress is an important tumor suppression mechanism of SOCS1 in HCC." (PMID 38254783, 2024). "Thirdly, we have shown that SOCS1 is critical to regulate the tumor suppressor functions of the cyclin-dependent kinase inhibitor CDKN1A (p21) by preventing its cytosolic retention, which can render it oncogenic." (PMID 38254783, 2024). "The results show that the group with lower SOCS1 expression had reduced stromal, immune, and ESTIMATE scores compared to the group with higher expression, implying a decreased tumor purity in those with elevated SOCS1 expression." (PMID 39654174, 2024). "Suppression of SOCS-1 can enhance antitumor immunity or promote tumor-promoting inflammation, depending on the cell type." (PMID 38482001, 2024). "MiR-6794-5p, which was upregulated by Bcl-w which is highly expressed in tumor cells, increased tumorigenicity by suppressing SOCS1 expression." (PMID 38521953, 2024). "It restrains the effector functions of tumor reactive CD8+ T cells as transduction of with Socs1-targeting microRNA miR-155 into these cells enhances their cytokine responsiveness resulting in improved efficiency to control tumors." (PMID 38415248, 2024). "SOCS1 has also emerged as a key checkpoint that restricts anti-tumor immunity, playing both a tumor intrinsic role and impacting the ability of various immune cells to mount an effective anti-tumor response." (PMID 38947335, 2024). "Investigations into the tumor suppression mechanisms so far focused on tumor cell-intrinsic functions of SOCS1." (PMID 38415248, 2024). "Clinical data and genetic models support independent tumor suppressor functions of SOCS1 and SOCS3 in the liver." (PMID 36765862, 2023). "Among the four model genes, SOCS1 is a widely recognized tumor suppressor gene, and its downregulation has been detected in various malignant tumors, including AML." (PMID 37845004, 2023). "In MF, one-copy deletion of SOCS1 was detected in early-stage lesions and SOCS1 was found to be a tumor suppressor frequently deleted in MF." (PMID 37664523, 2023). "All Socs1fl/flAlb-Cre mice developed numerous and large tumor nodules and showed increased liver-to-bodyweight ratio compared to Socs1fl/fl control mice, confirming the tumor suppressor role of SOCS1 in hepatocytes." (PMID 36765862, 2023). "In this regard, the dichotomic participation of SOCS1 in cancer has been extensively discussed since, depending on the tumor stage, it displays both tumor-promoting or antitumor activities." (PMID 37916165, 2023).
tumor (continued). "SOCS1 binds growth factor receptors and inhibits signaling through downstream receptor tyrosine kinases, sensitizing tumor cells to apoptosis and direct killing." (PMID 37711623, 2023). "SOCS1 and SOCS3 were important negative regulators of tumor-associated immune cells during tumor development, PE inhibited the activation of JAK2 in SOCS1." (PMID 37355637, 2023). "Comparing the expression of the CDDP-DTP-associated genes between tumor and normal adjacent tissue, and its clinical relevance, we found that six (GADD45A, SOCS1, EPS15, GLI3, NR2F2, and RCOR1) of the hub genes have significant differences." (PMID 37916165, 2023). "With respect to the findings of SOCS1 in the OS of patients, which appear to be contrary to those reported in tumor tissue, overexpression of SOCS1 correlates with poor OS of the CDDP-treated LUAD patients." (PMID 37916165, 2023). "In the immunohistochemistry experiments, SOCS1 was more highly expressed in HPV-negative HNSCC tumor tissues compared to HPV-positive HNSCC tissues (p < 0.05)." (PMID 37504269, 2023). "The expression levels of SOCS1, Ki-67, E-cadherin, and N-cadherin in tumor tissues were measured by immunohistochemical staining." (PMID 37009803, 2023). "We outline the potential mechanism of SOCS1 as a tumor suppressor and discuss the new evidence of SOCS1 activity as an oncogene." (PMID 36199788, 2022). "Taken together, our in vitro and in vivo data using miR-155–KO tumor cells further confirms the antitumor role of endogenous miR-155 in regulating antitumor immune response by targeting SOCS1 and altering its downstream p-STAT1/p-STAT3 balance." (PMID 35925680, 2022). "As for SOCS1, a biomarker with the largest protective coefficient in our study, was widely recognized as a tumor suppressor." (PMID 36249755, 2022). "The tumor-specific component of the ICI resistance was due to genetic loss of IFNGR1/2 and JAK2, and amplification of IFN signaling inhibitors SOCS1 and PIAS4." (PMID 35269844, 2022). "miR-155 promotes the accumulation of functional MDSCs in the tumor microenvironment (TME) via suppressing suppressor of cytokine signaling 1 (SOCS1) signaling and reducing the generation of Treg cells." (PMID 36569895, 2022). "Lastly, the silencing of SOCS1 expression observed in hepatocytes compared to stem cells has also been observed through changes in DNA methylation in tumor cells." (PMID 36439639, 2022). "In CD8+ T cells, miR-155 repressed suppressor cytokine signaling-1 (SOCS1), and miR-155 overexpression or SOCS1 inhibition in CTLs further enhanced anti-tumor immunity." (PMID 36248881, 2022). "In the case of HCC, the complexity is further illustrated by evidence implicating SOCS1 as both a tumor suppressor and oncogene based on its level of expression in tumor cells." (PMID 36439639, 2022). "Tumor-associated DCs (TADCs) express elevated miR-148a, which represses DNA methyltransferase (DNMT) 1 and causes subsequent hypomethylation of SOCS1, a suppressor of TLR signaling." (PMID 36248881, 2022). "RNF7 overexpression inhibited apoptosis and promoted glycolysis in vitro and increased tumor growth in vivo by activating the JAK/STAT3 signaling pathway by ubiquitination of SOCS1." (PMID 35562668, 2022). "Our results showed that with tumor progression, the expression of SOCS1 in peripheral blood G-MDSCs was gradually downregulated." (PMID 35013108, 2022).
tumor (continued). "The results showed that compared with the sham group, the SOCS1 expression levels in mice tumor tissues of the three UBE treatment groups and the UBE + PEM group were significantly increased (P < 0.05) and were concentration dependent." (PMID 35789603, 2022). "The SOCS1 protein is often repressed in HCC and the incidence of aberrant methylation in the CpG island of SOCS1 has been reported to be 65% in 26 human primary HCC tumor samples." (PMID 35626153, 2022). "The results showed that the transcriptional expression levels of NDRG1 (P < 0.001), ERRFI1 (P < 0.001), IRS2 (P < 0.001), IGFBP4 (P < 0.01), and BIRC3 (P < 0.01) were significantly decreased in tumor tissues, while SOCS1 (P < 0.05) expression was increased." (PMID 35859293, 2022). "Non-tumoral and peri-HCC livers were dominated by unmethylated SOCS1 (62% and 53%, respectively), while partially methylated and methylated SOCS1 were noticed in a small number of samples (Non-tumor: 24% and 14%; peri-HCC: 33% and 13%, respectively)." (PMID 34679523, 2021). "Results showed significant upregulated expression of certain genes like Hgf, Hmga1, Rasgrp1, Sh2b2, Socs1, Socs2, and Socs3 in WT mice tumor compared to its ChREBP systemic knockout tumor." (PMID 34685767, 2021). "Intratumoral injection with an adenovirus expressing SOCS1 in nude mice resulted in significantly reduced tumor volumes." (PMID 34639015, 2021). "SOCS1 ablation in human DCs was shown to be required to break self-tolerance in order to induce anti-tumor responses, resulting in enhanced activation of DCs, increased IFN-γ and enhanced killing by cytotoxic T cells." (PMID 34604264, 2021). "Only three studies on BRCA were found that showed statistically significant differences in SOCS1 expression: two showed increased expression, and one showed decreased expression in tumor tissues compared with normal tissues." (PMID 34120621, 2021). "Modified DC (gmDC) vaccine: The adenovirus (Ad-siSSF) delivers two tumor-associated antigens (TAAs), survivin and MUC1; secretory bacterial flagellin for DC maturation; and an RNA interference moiety to suppress SOCS1." (PMID 33937323, 2021). "The incidence of SOCS1 aberrant DNA methylation was around 60% in HCC tumor specimens, indicating it is a common event in HCC." (PMID 34679523, 2021). "The suppressor of cytokine signaling 1 (SOCS1) is a tumor-suppressor gene and suppresses cytokine signaling and destroys the HPV E7 protein." (PMID 35096000, 2021). "SOCS1 acts as an antioncogene in various tumors, arresting the cell cycle, inhibiting cancer cell migration and invasion, and attenuating tumor growth." (PMID 34398824, 2021). "The suppressor of cytokine signaling 1 (SOCS1) is a tumor suppressor gene found to be hypermethylated in cancers." (PMID 34679523, 2021). "Destabilization of Treg cells by a deficiency of critical Treg-associated factors such as Nrp-1, SOCS1, EZH2, Eos or CARMA1 protects hosts from syngeneic tumor growth." (PMID 33024109, 2020). "This demonstrated an EV-mediated interaction of tumour promotive effects through promotion of M2 macrophage differentiation, mediated by EV-transferred miR-20a-3p via the SOCS1/STAT6 signalling pathways." (PMID 32054041, 2020). "Since IL6 upregulates SOCS-1, which is a negative regulator of JAK-STAT signaling cascade, we next examined the methylation pattern of SOCS-1 gene promoter in tumor tissues." (PMID 33569347, 2020). "The suppressor of cytokine signaling 1 (SOCS1) gene has a dual opposite, it can function as either a tumor suppressor or a tumor promoter." (PMID 32758256, 2020). "As a whole, our study revealed a novel tumor-promoting mechanism involving LINC00669/SOCS1/STAT1 regulatory network in NPC." (PMID 32831137, 2020). "We found that SOCS-1 gene promoter was methylated in majority of tumor specimens (partially methylated in ~75% and fully methylated in ~15% of tumor specimens)." (PMID 33569347, 2020).